IFNG (interferon gamma)
Diseases named in the same sentence as IFNG in open-access papers (continued):
Sharing a sentence is not in itself a finding about the gene and the disease.
Obesity (continued). "Given that JAK2 plays a critical role in brown adipose tissue function and diet-induced thermogenesis in HFD mice, JAK2 signaling between leptin and IFNγ may play a critical role in obesity-related inflammation and metabolic disorders." (PMID 33379198, 2020). "Recent studies have shown that IFNγ may play a crucial role in obesity-related inflammatory response." (PMID 30862026, 2019). "LTBI remained associated with higher unstimulated interferon-gamma levels after controlling for age, sex, recent AMI, history of hypertension, diabetes mellitus, dyslipidemia, end stage renal disease, malignancy, obesity, and tobacco use (adjusted odds ratio, 2.93; 95% confidence interval, 1.8–4.9)." (PMID 30212453, 2018). "In contrast, obesity causes alteration of the constituent immune cells, in which TH1 cells, B cells, neutrophils, or mast cells induce M1 activation of macrophages by the elevated secretion of TNFα and IFNγ." (PMID 23964268, 2013). "Similar results were observed with interferon gamma, another Th1 cytokine implicated in adipose tissue inflammation in diet-induced obesity, except that the difference was no longer apparent after 10 weeks." (PMID 21085605, 2010). "In addition, many studies have shown that pro-inflammatory cytokines, such as tumor necrosis factor (TNF), interleukin 6 (IL-6), IL-1β, and interferon-gamma (IFN-γ), can influence insulin resistance, adipose tissue inflammation and regulate obesity-related metabolism." (PMID 40931194, 2025). "Overall, monocytes from adolescents with obesity have a transcriptionally distinct and pro-inflammatory phenotype with increased transcriptional responses upon LPS stimulation compared to control children, whilst having a decreased IFNg signature at the same time." (PMID 38741712, 2024). "Regarding adaptive immunity, studies employing cafeteria diet-induced obesity as well as the alloxan-induced model of diabetes in rats have reported that PCs intake lowered the production of pro-inflammatory mediators including ILs, TNFα, IFNγ and TGF-β by MLN and splenic lymphocytes." (PMID 38558823, 2024). "Being inversely correlated with obesity and visceral adiposity, adiponectin supports interleukin 10 (IL-10) expression and inhibits the nuclear factor kappa light-chain-enhancer of activated B cells (NFκB), influencing interferon gamma (IFNγ) production in monocyte-derived cells." (PMID 39518420, 2024). "Therefore, increased IL-10 levels in the placebo group might represent feedback from elevated pro-inflammatory cytokines upregulated in obesity, including IFNγ." (PMID 36771387, 2023). "Three genes (ITK, SLFN5, STK10), which have not been linked to diabetes yet, might interact with IFNG and thereby contribute to inflammatory mechanisms usually triggered by obesity." (PMID 32350386, 2020). "IFNγ, previously shown to accompany hepatic steatosis in mice, may directly induce endoplasmic reticulum stress, a potential contributor to the vicious cycle of obesity and chronic inflammation." (PMID 27555877, 2016). "Additionally, obesity and insulin resistance compound acne-related inflammation through the secretion of pro-inflammatory adipokines like leptin, which promotes Th1 and Th17 polarization and increases cytokines such as interferon-gamma (IFN-γ), IL-17, and IL-22." (PMID 39858932, 2025). "Previously, it was reported that DSC juice supplementation lowered obesity-related biomarkers such as SBP and DBP as well as decreased pro-inflammatory interferon gamma (IFNγ) in obese adults." (PMID 40077655, 2025). "NK cells are also dysfunctional in contexts of obesity and T2DM, displaying increased proliferation rates and IFNγ secretion, and impaired degranulation, respectively." (PMID 38558823, 2024). "Conversely, in obesity tumor models, activated STAT3 promotes FAO while inhibiting glycolysis and IFNγ production in CD8+ effector T cells." (PMID 39402302, 2024).
Obesity (continued). "Circulating MAITs in obesity and metabolic disease are characterized by increased IL2, granzyme B, IL17, IFNγ, and TNFα, and less IL10 compared to healthy controls." (PMID 38674935, 2024). "Other cytokines, associated with type 1and 2 T-helper cell responses such as interferon-gamma (IFN-γ), IL-2, IL-4, IL-3 and TNF-α, are primarily involved in inflammatory responses that include alopecia areata, obesity, diabetes and laminitis." (PMID 39148726, 2024). "Other studies showed that circulating levels of amyloid A protein, interferon-gamma (IFN-γ), interleukin-6 (IL-6), tumor necrosis factor alpha (TNF-α), and C-reactive protein (CRP) were prominently reduced in patients with obesity by CR." (PMID 37755259, 2023). "During obesity, macrophages infiltrate and produce cytokines such as tumor necrosis factor-alpha (TNF-α), interleukin 1 beta (IL-1β), IL-18, IL-6, and interferon-gamma (IFN-γ)." (PMID 37214340, 2023). "The higher transcription of mRNA FOXP3 and IL-10 (Treg markers), accompanied by a high transcription of TBX21 and IFNG (Th1 markers), GATA3 and IL-4 (Th2 markers) indicated the inflammatory status in the group with obesity and an altered Treg function." (PMID 37215211, 2023). "The obesity-induced pro-inflammatory shift of immune cells is a condition that favors the release of pro-inflammatory cytokines (TNF and IFNγ) and goes hand in hand with a reduction in the release of protective cytokines (IL-10 and IL-22) and adipokine." (PMID 36648872, 2022). "In obesity, adipose tissue produces cytokines such as interleukin (specifically IL1ß and IL6), interferon γ (IFNγ), Tumor Necrosis Factor α (TNFα), and Monocyte Chemoattractant Protein 1 (MCP1), which promote chronic inflammation." (PMID 36009143, 2022). "The dual effects of IFNγ likely explain the inverse relationships of MHCII pathway genes and metabolic pathway genes in the adipocyte in obesity." (PMID 36153324, 2022). "Obesity reduces T lymphocytes, B lymphocytes, natural killer cell activity, the antibody and IFN-γ (Interferon-gamma) production." (PMID 34071441, 2021). "Obesity simultaneously promotes hyperactivation of CD8 tumor-infiltrating lymphocytes (TILs), as evidenced by increased expression of CD44, PD-1, Ki-67, IFNγ, and the death receptor Fas." (PMID 33123173, 2020). "Accordingly, increases were seen in the percentages of PD-1+, Ki-67+, and IFNγ+ CD8 TILs, consistent with increased antigen engagement, proliferation, and cytokine production with obesity." (PMID 33123173, 2020). "Given that IFNγ and TNFα were determined to be top transcriptional regulators in HFD mice, it is likely that M1 macrophages are strongly activated in obesity." (PMID 33379198, 2020). "Since IL-15 is induced by inflammatory stimuli, and several inflammatory cytokines such as IL-6, TNFα, IFNγ are implicated in promoting obesity and insulin resistance, we postulated that IL-15 might contribute to the pathogenesis of obesity rather than conferring protection against it." (PMID 27684068, 2016). "In obesity, inflammatory mediators such as IL-1β, TNF-α, and interferon gamma can elevate the CCR6 expression level." (PMID 27869712, 2016). "The obesity-related adipose gene expression pattern was dramatically altered by the HF-FO diet, whereby expression of MCP-1, IL-6 and IFNγ mRNA levels were reduced and IL-10 mRNA expression was elevated, compared to HF." (PMID 23166761, 2012). "This study was a secondary analysis of a single-arm weight loss clinical trial for adults with obesity, which aimed to investigate the effects of ADF-LC on circulating immune response biomarkers that are modulated by obesity including PD-L1, CCL2, CCL4, IL-8, IL-1ra, IFNγ, CD40-L, and IP-10." (PMID 40145019, 2025).
Obesity (continued). "This influx of inflammatory immune cells into obese adipose tissue promotes the production of inflammatory cytokines such as tumor necrosis factor (TNF), interleukin-6 (IL-6), and interferon gamma (IFN-γ), which contribute to the chronic inflammatory state (metaflammation) observed in obesity." (PMID 37276236, 2023). "Adipose tissue, which expands and undergoes remodeling during obesity, contributes to vascular EC dysfunction by secreting vasoconstrictor mediators and proinflammatory cytokines such as TNF-α, interferon-gamma (IFNγ), interleukin-1β (IL-1β), and interleukin-6 (IL-6)." (PMID 37174741, 2023). "During obesity, ATMs display increased major histocompatibility complex II (MHCII) and co-stimulatory molecules to activate CD4 + T cell proliferation and pro-inflammatory interferon-gamma (IFN-γ) production." (PMID 35456015, 2022). "In contrast, obesity triggers the secretion of cytokines involved in osteoporosis, negative vessel remodeling, and inflammation with increased leukemia inhibitory factor (LIF), IL1β, CCL2, leptin, interferon gamma (IFNγ), IL6, and TNFα." (PMID 36010901, 2022). "In separate studies examining the impact of obesity on T-cell antiviral immunity, obesity was found to negatively impact the percentage of Vγ9Vδ2 T cells, an IFNγ-secreting γδ T-cell subset." (PMID 36140808, 2022). "Macrophages from mothers with obesity failed to induce CD86 upregulation following IFNγ stimulation (right), while HLA-DR induction was comparable between the two groups." (PMID 34195568, 2021). "Concomitantly, markers of endothelial dysfunction correlated with cytokines levels of the Th1 immune orientation (IFNγ, TNFα), inflammation (IL-17a, MIP1α, G-CSF, TNFα, MIP1β, and IFNγ), and/or M1 activation (IL-6, IFNγ, TNFα, IP10, MIP1α, and MCP1), mostly in patients with obesity." (PMID 34038475, 2021). "In this study, we found that HIF-1α mediates MCP1, TNFα, and IFNγ production and that HIF-1α-mediated impairment of liver and EWAT increases IL-1β production, which induced M1 polarization in mice contributing to obesity-induced NAFLD." (PMID 34360607, 2021). "During obesity, the pro-inflammatory skewing of immune cells favors the release of cytokines such as TNF and IFNγ, coupled with a reduction in IL-10, IL-17, and IL-22, resulting in reduced expression of epithelial tight junction proteins, mucin, and antimicrobial proteins such as RegIIIγ2,33." (PMID 33972511, 2021). "The top differentially expressed genes affected by upstream transcriptional regulators IFNγ, LPS, and TNFα displayed an overlap in HFD and ARE-Del-/- mice, indicating that obesity-induced liver inflammation may be dependent on signaling via IFNγ." (PMID 33379198, 2020). "Obesity did not alter the percentages of circulating IFNγ+ CD8 T cells or IFNγ+, IL-4+, or IL-17A+ CD4 T cells in ccRCC subjects." (PMID 32469992, 2020). "Evaluation of CD8+ PMBC cytokine production revealed no changes in IFNγ production in ccRCC subjects or tumor-free donors with obesity (one-way ANOVA, P = 0.2690)." (PMID 32469992, 2020). "Actually, the lack of association in our study between Akkermansia and other clinical hard end-points, such as obesity or related immune mediators, such as MCP-1 or IFNγ, may support a very early role of these features." (PMID 28791008, 2017). "Consistent with previous reports of obesity-prone C57BL/6 mice responding to a high-fat diet with the induction of a proinflammatory response, this work demonstrates increased spleen production potential of IFNγ, IL1β, and IL-17." (PMID 20877574, 2010). "During obesity, adipocytes increase their expression of NK cell activating receptor (NCR1) which may be responsible for the expansion of local VAT NK cells and their IFNγ production." (PMID 32499756, 2020).
Obesity (continued). "ILC1s are mainly involved in the early protection against virus and bacteria through the secretion of interferon-gamma (IFN-γ) and granulocyte-macrophage colony-stimulating factor (GM-CSF), however their dysregulation in adipose tissues leads to the development of metabolic disorders and obesity." (PMID 30915072, 2019). "However, in AT, IFNγ is secreted by recruited inflammatory cells, and not by adipocytes, especially in obesity." (PMID 30654824, 2019). "Additionally, immune molecules, including interferon gamma (INF-γ), interleukin (IL)-7, IL-10, and α-melanocyte-stimulating hormone-reactive immunoglobulin G (α-MSH/IgG) immune complex, may have negative associations with obesity-related eating behaviors." (PMID 35911732, 2022). "In particular, a HFD led to an upregulation of genes such as toll-like receptor 4 (TLR4), NF-κB, Cd68, Emr1, IL-6, indoleamine 2,3-dioxygenase (IDO), TNF-α, and interferon gamma (IFN-γ) in rodents, suggesting that these changes were related to diet-induced changes rather than obesity." (PMID 31731503, 2019).
diabetes (319 papers, 2007 to 2026). "To test this mechanism in humans, we exposed isolated pancreatic islets from human donors to the diabetes-associated proinflammatory cytokines IL-1β and IFNγ, and evaluated the effects of fenofibrate on beta cell function and death." (PMID 39477880, 2025). "Pro-inflammatory cytokines, like interleukin-1 beta and interferon gamma, are known to activate signalling pathways causing pancreatic beta cell death and dysfunction, contributing to the onset of diabetes." (PMID 39774736, 2025). "Diabetes associates with a whole-body low-grade inflammatory status characterized by elevated production of circulating cytokines such as IL-6, TNFα, IFNγ, TGFβ, MCP1, or IL-1b." (PMID 34623540, 2023). "Multiple underlying environmental conditions, immune, and host genetic predisposing factors have been associated with TB infection, such as HIV infection, diabetes, and deficiency in interferon-gamma (IFN-γ) encoding genes." (PMID 37609282, 2023). "In mice, antibodies against IFNγ decrease the incidence of cyclophosphamide-induced diabetes and IFNγ-deficient mice are resistant to virus-induced diabetes." (PMID 36611907, 2022). "On the contrary, HCV infection has been shown to be associated with IFNG and the development of type 2 diabetes mellitus in general population." (PMID 33727573, 2021). "IFNγ takes part in the pathogenesis of diabetes, and the frequency of the low IFNγ production allele (the A allele) was considerably higher in patients with type 2 diabetes compared with the control group." (PMID 32751810, 2020). "LTBI remained associated with higher interferon-gamma concentrations after adjusting for age, gender, race, diabetes, hypertension, tobacco use, HIV status, body mass index, lipid profile, and lymphocyte count (odds ratio, 1.79, 95% CI, 1.26 – 2.53)." (PMID 27853753, 2016). "Since IFNγ-deficient NOD mice develop diabetes essentially like their wild-type counterparts, yet IFNγ plays a critical role in CFA-mediated protection from T1D45, it is likely that this cytokine can have both pro- and anti-inflammatory properties in a context-dependent manner." (PMID 35672409, 2022). "Multiple-antioxidant therapy prevented higher expression of tumor necrosis factor alpha (TNF-α), interferon gamma (IFN-γ), and ROS-producing enzymes in a type 1 diabetes mellitus (T1DM) model, clearly supporting an association of oxidative stress, inflammation, and diabetic complications." (PMID 32408480, 2020). "In line with our observations in the pancreases from patients with diabetes, exposure of islets to diabetogenic conditions in vitro led to a loss of Siglec-7 expression, in particular, treatment of islets with a mixture of 22.2 mM glucose/0.5 mM palmitate as well as with the cytokines IL-1β/IFNγ." (PMID 28378743, 2017). "Although diabetes generally promotes persistent inflammatory responses, controlled acute inflammation—mediated by cytokines such as interferon-gamma (IFN-γ)—is crucial for effective tissue repair and regeneration." (PMID 41602470, 2026). "In animal studies, it was demonstrated that mice with streptozotocin-induced diabetes exhibited markedly elevated expression of interferon-gamma mRNA in cardiac tissues relative to control mice." (PMID 40260277, 2025). "For another eight biomarkers (TNFβ, GDNF, IL-18R1, LIF-R, CD244, CD6, FGF-5, IFNγ), a significant interaction by diabetes type was observed." (PMID 39799156, 2025). "Interferon-gamma (IFN-γ), primarily secreted by T helper 1 (Th1) cells, is a key inflammatory cytokine involved in the pathogenesis of diabetes and is closely associated with secondary infections in diabetic foot ulcers." (PMID 40677522, 2025). "HBV-induced liver cirrhosis patients exhibit elevated levels of S100A8/A9, natural killer (NK) cells, and interferon-gamma (IFN-γ) following STAT3 activation, a biomarker profile associated with diabetes development." (PMID 40918255, 2025).